SH3BGR (SH3 domain binding glutamate rich protein)
Synonyms: 21-GARP
Tractability: Antibody: the Human Protein Atlas places it where antibodies can reach.
Gene: Protein-coding gene on chromosome 21 (39,445,855 to 39,515,506, forward strand). Ensembl gene ENSG00000185437.
Subcellular location (Human Protein Atlas): Cytosol; Plasma membrane
Gene Ontology:
Molecular function: protein binding; protein-macromolecule adaptor activity
Cellular component: nucleus
Genetic constraint (gnomAD): Loss-of-function variants: 16 observed, 12.79 expected, observed/expected ratio (o/e) 1.25, 90% interval 0.84 to 1.81. The upper end of that interval is the gene's LOEUF score, 1.81, which puts it in group 6 of 6, group 1 being the genes least tolerant of losing a copy. Missense variants: 102 observed, 135.71 expected, observed/expected ratio (o/e) 0.75, 90% interval 0.64 to 0.89. Synonymous variants: 35 observed, 45.41 expected, observed/expected ratio (o/e) 0.77, 90% interval 0.59 to 1.02.
Homologues: Orthologues: chimpanzee SH3BGR (95% identical), macaque GET1 (84% identical), pig SH3BGR (82% identical), dog SH3BGR (74% identical), guinea pig SH3BGR (67% identical), mouse Sh3bgr (62% identical), rat Sh3bgr (61% identical), zebrafish sh3bgr (55% identical), tropical clawed frog sh3bgr (54% identical), rabbit SH3BGR (52% identical). Paralogues in human: SH3BGRL (41% identical), SH3BGRL2 (39% identical), SH3BGRL3 (22% identical).
Diseases named in the same sentence as SH3BGR in open-access papers:
SH3BGR is named in the same sentence as 16 diseases in open-access papers, as found by Europe PMC text mining. Sharing a sentence is not in itself a finding about the gene and the disease. The quoted sentences say what the papers report.
congenital heart defect (4 papers, 2005 to 2024). "This study reveals novel insights into DS cardiac pathology, highlighting the intricate role of METTL3 in DS congenital heart defects and presenting the m6A modification of SH3BGR as a potential therapeutic target." (PMID 39237501, 2024). "To elucidate the pathogenetic mechanisms underlying this condition, we explored the role of RNA m6A methylation, regulated by METTL3, in DS cardiac development and its impact on the expression of SH3BGR, a gene located at Down syndrome congenital heart disease (DS-CHD) minimal region." (PMID 39237501, 2024).
Down syndrome (4 papers, 2016 to 2024). "SH3BGR was first reported in association with the critical region for Down’s syndrome on chromosome 21." (PMID 34681711, 2021). "First discovered in 1997, SH3BGR is associated with the critical region of Down’s syndrome on human chromosome 21." (PMID 34681711, 2021). "Several genes associated previously with heart anomalies in Down syndrome, SH3BGR, DCSR6 and ADAMTS1, were co-injected (30pg each)." (PMID 29760202, 2018). "The SH3BGR gene, encoding a SH3 domain-binding glutamic acid-rich protein, is located on chromosome 21, within the genetic region associated with Down syndrome." (PMID 39237501, 2024). "Here, using NRVCM as an in vitro study model, we aimed, on one hand to find if increased levels of SH3BGR, as found in Down’s syndrome, affects the cardiomyocyte function." (PMID 34681711, 2021). "This enriches our understanding of the mechanisms behind the increased expression of SH3BGR in Down syndrome, suggesting the m6A modification of SH3BGR could serve as a potential therapeutic target." (PMID 39237501, 2024). "However, the specific roles of SH3BGR in Down syndrome cardiac development remain unclear." (PMID 39237501, 2024). "In contrast, Down syndrome features abnormal METTL3 expression, which post-transcriptionally enhances SH3BGR mRNA." (PMID 39237501, 2024).
cardiac hypertrophy (2 papers, 2021 to 2024). "Altogether, striated muscle-specific expression, coupled with sarcomeric localization and upregulated protein levels in cardiac hypertrophy, indicates SH3BGR plays an important role in cardiac pathophysiology." (PMID 34681711, 2021). "We observed alterations in SH3BGR levels in the heart of patients with cardiac hypertrophy as well as in the hearts of mouse model of cardiac hypertrophy due to biomechanical stress (TAC)." (PMID 34681711, 2021). "Notably, SH3BGR is significantly upregulated in the hearts of human patients with cardiac hypertrophy and in a mouse model of heart failure induced by transverse aortic constriction, suggesting its involvement in cardiac hypertrophy." (PMID 39237501, 2024). "We observed significant upregulation of SH3BGR in the hearts of human patients suffering cardiac hypertrophy and a mouse model of heart failure due to transverse aortic constriction, consequently pointing towards its potential involvement in cardiac hypertrophy and associated modalities." (PMID 34681711, 2021).
Down syndrome congenital heart disease (2 papers, 2016 to 2024). "The gene SH3BGR, residing in the Down syndrome congenital heart disease (DS-CHD) minimal region, is selectively transcribed in the heart and skeletal muscle." (PMID 39237501, 2024). "SH3BGR is involved in the pathogenesis of Down syndrome congenital heart disease and obesity." (PMID 27128969, 2016).
bladder cancer (1 paper, 2022). "Another top-ranked gene was SH3BGR, a family of genes that might indicate a low survival rate in bladder cancer in its subtype SH3BGRL3." (PMID 36175974, 2022).
hypertrophic cardiomyopathy (1 paper, 2021). A condition in which the myocardium is hypertrophied without an obvious cause. "Interestingly, we observed a significant upregulation of SH3BGR in failing hearts of mice and human patients with hypertrophic cardiomyopathy." (PMID 34681711, 2021).
renal cell carcinoma (1 paper, 2021). "As recent literature postulated SH3BGRL2, a homolog of SH3BGR, to affect the Hippo signaling pathway in renal cell carcinoma, we aimed to find whether SH3BGR affects Hippo signaling in neonatal cardiomyocytes." (PMID 34681711, 2021).
cardiac disease (1 paper, 2019). "Other genes have not been implicated in heart diseases (ADPRHL1, KLHL38, SH3BGR)." (PMID 31641117, 2019). "MYBPC3, TTN and SCN5A are established cardiac disease genes, but SH3BGR and HMCN2 are not." (PMID 31641117, 2019).
SH3BGR also shares sentences with these, for which no sentence is quoted: bipolar disorder (1 paper); cancer (1); heart failure (1); hyperthymia (1); non-small cell lung carcinoma (1); Obesity (1); trisomy (1); tumor (1).